BLMH (bleomycin hydrolase)
Description:
The normal physiological role of BLM hydrolase is unknown, but it catalyzes the inactivation of the antitumor drug BLM (a glycopeptide) by hydrolyzing the carboxamide bond of its B-aminoalaninamide moiety thus protecting normal and malignant cells from BLM toxicity.
Synonyms: BH; BMH
Tractability: Small molecule: it has a high-quality binding pocket. PROTAC: ubiquitination databases record sites on it; its protein half-life has been measured.
Target class: Enzyme; Hydrolase
Safety:
Unwanted effects reported when the protein is acted on. In parentheses: how it was acted on, where the effect was seen, and who reports it.
alopecia (source: ClinPGx)
pain (source: ClinPGx)
Gene: Protein-coding gene on chromosome 17 (30,248,200 to 30,292,152, reverse strand). Ensembl gene ENSG00000108578.
Subcellular location: Cytoplasm; Cytoplasmic granule
Subcellular location (Human Protein Atlas): Cytosol; Nuclear bodies; Nucleoplasm
Pathways (Reactome):
Immune System: Antigen processing: Ubiquitination & Proteasome degradation
Gene Ontology:
Molecular function: aminopeptidase activity; identical protein binding; protein binding; carboxypeptidase activity; cysteine-type endopeptidase activity; cysteine-type peptidase activity; cysteine-type aminopeptidase activity; peptidase activity
Biological process: homocysteine catabolic process; protein polyubiquitination; proteolysis; response to toxic substance
Cellular component: cytoplasm; cytosol; extracellular exosome; nucleus
Genetic constraint (gnomAD): Loss-of-function variants: 23 observed, 45 expected, observed/expected ratio (o/e) 0.51, 90% interval 0.37 to 0.72. The upper end of that interval is the gene's LOEUF score, 0.72, which puts it in group 2 of 6, group 1 being the genes least tolerant of losing a copy. Missense variants: 368 observed, 469.41 expected, observed/expected ratio (o/e) 0.78, 90% interval 0.72 to 0.86. Synonymous variants: 148 observed, 167.72 expected, observed/expected ratio (o/e) 0.88, 90% interval 0.77 to 1.01.
Homologues: Orthologues: chimpanzee BLMH (99% identical), macaque BLMH (98% identical), dog BLMH (95% identical), rat Blmh (94% identical), mouse Blmh (93% identical), rabbit BLMH (93% identical), guinea pig BLMH (93% identical), pig BLMH (91% identical), tropical clawed frog blmh (73% identical), zebrafish blmh (71% identical), Drosophila melanogaster CG1440 (55% identical), Drosophila melanogaster CG13423 (34% identical).
Diseases named in the same sentence as BLMH in open-access papers:
BLMH is named in the same sentence as 24 diseases in open-access papers, as found by Europe PMC text mining. Sharing a sentence is not in itself a finding about the gene and the disease. The quoted sentences say what the papers report.
Alzheimer disease (5 papers, 2011 to 2025). A progressive, neurodegenerative disease characterized by loss of function and death of nerve cells in several areas of the brain leading to loss of cognitive function such as memory and language. "BLMH has been implicated in Huntington’s disease, through cleavage of huntingtin, and in Alzheimer’s disease through the processing of amyloid precursor protein." (PMID 32821252, 2020). "BLMH encodes the enzyme Bleomycin hydrolase that is a cytoplasmic cysteine peptidase and has been associated with the risk of development of Alzheimer's disease." (PMID 21479260, 2011). "In line with this, deficiencies in Hcy‐thiolactone–detoxifying enzymes, including paraoxonase 1 (PON1) and bleomycin hydrolase (BLMH), have been linked to Alzheimer's disease pathology, suggesting that inadequate clearance of Hcy‐thiolactone contributes to neurodegenerative risk." (PMID 41427720, 2025). "In addition to being studied in relation to Hcy toxicity and Alzheimer’s disease, BLMH was also studied in the field of protein turnover, cancer therapy, keratinization disorders, and asthma." (PMID 39125665, 2024). "Bleomycin hydrolase (BLMH), a homocysteine (Hcy)-thiolactone detoxifying enzyme, is attenuated in Alzheimer’s disease (AD) brains." (PMID 37718819, 2023).
colon carcinoma (3 papers, 2014 to 2025). "The expression pattern of BLMH varies among different tumor cell lines, as well as among cell lines originating from the same cancer type; i.e., the expression pattern of colon carcinoma cells (CT26 and MC38) or mammary carcinoma (TS/A and 4T1) was not similar." (PMID 41514636, 2025). "Bleomycin hydrolase (BLMH) is a kind of drug‐metabolizing enzymes that were highly expressed in drug‐resistant colon cancer stem cells, but no previous studies was conducted to detect the prognostic role of BLMH in colon cancer." (PMID 29377588, 2018). "Comparing the secretome of colon CSCs with that of more differentiated colon cancer cells in the bulk tumor they found that CSCs secreted much higher levels of aldehyde dehydrogenase family 1, member A1 (ALDH1A1) and bleomycin hydrolase (BLMH), two enzymes able to detoxify chemotherapeutics." (PMID 24728412, 2014).
atopic dermatitis (2 papers, 2019 to 2020). "BLMH is a filaggrin cleavage enzyme that generates natural moisturizing factors and whose levels are reduced in dry skin and atopic dermatitis." (PMID 32033114, 2020). "Interestingly, the expression and activity of BLMH is reduced in patients with atopic dermatitis (AD) and psoriasis, and BLMH knockout mice acquire tail dermatitis." (PMID 31892708, 2019).
breast carcinoma (2 papers, 2021 to 2025). "Bleomycin hydrolase and poly(ADP-ribose) polymerase-1 are reported to participate in the Ubc9-mediated resistance against chemotherapy agents in human breast carcinoma MCF-7 cells." (PMID 33499132, 2021).
hepatocellular carcinoma (2 papers, 2013 to 2020). A malignant tumor that arises from hepatocytes. "Besides, BLMH is also correlated with hepatocellular carcinoma." (PMID 32151087, 2020).
Hodgkins lymphoma (2 papers, 2016 to 2022). A heterogeneous group of malignant lymphoid neoplasms of B-cell origin characterized histologically by the presence of Hodgkin and Reed-Sternberg (HRS) cells in the vast majority of cases. "This may be explained by the relative deficiency of bleomycin hydrolase reported to occur in Hodgkin's lymphoma." (PMID 35665202, 2022).
Huntington disease (2 papers, 2020 to 2023). Huntington disease (HD) is a rare neurodegenerative disorder of the central nervous system characterized by unwanted choreatic movements, behavioral and psychiatric disturbances and dementia. "BLMH has also the ability to generate N-terminal fragments of huntingtin, thought to be important mediators of the pathogenesis of Huntington’s disease." (PMID 37718819, 2023).
alopecia (1 paper, 2019). Hair loss usually from the scalp. "Grades III–IV vomiting, nausea, and alopecia could be partly explained by the presence of specific ERCC1/2, MDR1, GSTP1, and BLMH genotypes (p < 0.05)." (PMID 30914949, 2019). "Grades III–IV vomiting, nausea and alopecia could also be partly explained by the presence of specific ERCC1/2, MDR1, GSTP1, and BLMH genotypes." (PMID 30914949, 2019).
B cell lymphoma (1 paper, 2017). "As a feasibility test, we first queried predicted DH for three genes FBL, LIN28A and BLMH in P493-6 B cell lymphoma (for which no public DNase-seq data are available) and H9 human embryonic stem cells." (PMID 29051481, 2017).
cholesteatoma (1 paper, 2015). A pathologic process characterized by the proliferation of keratinizing squamous epithelium resulting in the accumulation of keratin and cells in the middle ear and/or mastoid. "Increased BLMH levels in cholesteatoma relative to mucosa, but unchanged in skin, is logical given that it is found primarily in the superficial and corneal layers of epidermis which are largely deficient in the non-keratinizing middle ear epithelium." (PMID 26608071, 2015).
deep vein thrombosis (1 paper, 2021). "Bleomycin hydrolase (BLMH) was recently identified as a novel diagnostic plasma biomarker for deep vein thrombosis." (PMID 34768685, 2021).
liver diseases (1 paper, 2020). "BLMH is an aminohydrolase and is related to some liver diseases." (PMID 32151087, 2020).
multiple myeloma (1 paper, 2021). "A higher expression of the aminopeptidase genes XPNPEP1, RNPEP, DPP3, and BLMH in multiple myeloma plasma cells was associated with shorter patient overall survival." (PMID 33810334, 2021).
cancer (9 papers, 2010 to 2025). A tumor composed of atypical neoplastic, often pleomorphic cells that invade other tissues. "Many studies have attempted to identify the genetic variant(s) that underlie bleomycin-response differences across cancer patients, and some have identified potential connections between the metabolic enzyme bleomycin hydrolase (BLMH) and patient outcomes." (PMID 31171655, 2019). "BLMH, a highly conserved cytoplasmic cysteine peptidase, metabolically inactivates bleomycin, a key component in many cancer chemotherapy regimens." (PMID 41514636, 2025). "One example is Bleomycin hydrolase (the mammalian homologue of yeast Gal6), a peptidase complex (6 × 40 kDa), which is upregulated in some cancer cells and with an ability to bind double- and single-stranded DNA." (PMID 20847939, 2010). "The known role of the peptidase BLMH is to cleave the anti-cancer peptide Bleomycin, reducing the intracellular levels of the drug, but its primary biological function remains unknown." (PMID 36880517, 2023). "BLMH may have multiple roles in different physiological and pathological conditions, such as resistance to bleomycin therapy in several cancer types, cellular detoxification, and training of peptides for antigen presentation." (PMID 33810334, 2021). "Additional hits were Lysozyme C, Bleomycin hydrolase, Interleukin-36 gamma, AMBP (alpha-1-microglobulin/bikunin precursor), Ganglioside GM2 activator, and Beta globin—which are indicative of cancer cell survival." (PMID 40725142, 2025). "The production of bleomycin analogues that are not cleaved by human bleomycin hydrolase will result in bleomycin analogues that are more effective as an anti-cancer agent because the lung toxicity would be eliminated." (PMID 29734689, 2018).
tumor (5 papers, 2012 to 2025). "Correlations between BLMH expression and tumor response to ECT were assessed both in vitro and in vivo." (PMID 41514636, 2025). "In this study, we measured BLMH levels in different mouse tumor cell lines and tumors grown in animals." (PMID 41514636, 2025). "Some of them have been extensively studied and described in previous studies, while the current study focused on expression of BLMH in different tumor cell lines in vitro and tumor models in vivo." (PMID 41514636, 2025). "We observed a moderate correlation (R = 0.50) between mRNA BLMH expression and percentage of tumor complete response after ECT." (PMID 41514636, 2025). "Further studies should validate BLMH expression at the protein and activity levels, as well as in human tumor biopsies." (PMID 41514636, 2025). "The results of this study indicate that BLMH expression levels in tumor cells influence the therapeutic response to ECT." (PMID 41514636, 2025). "In vivo, BLMH expression levels moderately correlated with complete tumor response rates following ECT (R = 0.50)." (PMID 41514636, 2025). "Specifically, we aimed to evaluate BLMH levels in different tumor cell lines in vitro and evaluate BLMH levels in different murine tumor models in vivo." (PMID 41514636, 2025). "Differential BLMH expression among tumor types could explain variability in response to treatments such as ECT." (PMID 41514636, 2025). "Moreover, notable differences in BLMH expression can be observed in different tumor subtypes (TS/A and 4T1) with the same tissue origin." (PMID 41514636, 2025). "While BLMH is ubiquitously present in normal tissues, its expression levels vary considerably across cell types and organs, and it is also found in malignant tissues, where it may influence tumor sensitivity to bleomycin-based therapies." (PMID 41514636, 2025). "Again, BLMH was first determined in two tumor models, B16F10 and TS/A, both on an mRNA and protein level, to confirm that RNA levels of BLMH correlate relatively well with protein levels, also in vivo." (PMID 41514636, 2025). "The aim of this study was to investigate the role of BLMH as a predictive factor for the effectiveness of ECT in different tumor cell lines and murine tumor models." (PMID 41514636, 2025). "First, we determined in vitro expression of BLMH in two different tumor cell lines, B16F10 and TS/A, both on an mRNA and protein level, to confirm that there was a good correlation between RNA and protein levels of BLMH." (PMID 41514636, 2025). "Thereafter we compared the levels of BLMH with tumor response to ECT and found a correlation with BLMH content, i.e., tumors with higher BLMH content responded poorly." (PMID 41514636, 2025). "The lack of in vitro and in vivo BLMH expression can contribute to tumor hypoxia, which induces metabolic and redox stress by HIF signaling, which can downregulate enzymes involved in drug metabolism." (PMID 41514636, 2025). "This discrepancy highlights the need for careful evaluation of BLMH expression in clinically relevant tumor samples rather than relying solely on cell line models." (PMID 41514636, 2025). "Our data demonstrate a moderate in vivo correlation (R = 0.50) between tumor BLMH expression and CR rates, indicating BLMH is not the sole factor predicting tumor response." (PMID 41514636, 2025). "Given the variable BLMH content in different tissues and the lack of information on BLMH content in different tumor types, we hypothesize that BLMH activity reduces the effectiveness of ECT." (PMID 41514636, 2025). "We also observed a lack of correlation between in vitro and in vivo BLMH expression levels, which may be attributed to the complexity of the tumor microenvironment." (PMID 41514636, 2025).
infection (2 papers, 2019 to 2022). The state of being infected such as from the introduction of a foreign agent such as serum, vaccine, antigenic substance or organism. "In rainbow trout, BLMH expression has been identified as an innate response in the gill epithelial cell line to infection with ultraviolet-inactivated viral hemorrhagic septicemia virus." (PMID 36672855, 2022). "The BLMH rs1050565 G/G genotype was found to be associated with pain, and the GSTP1 G/G genotype was linked infection (p < 0.05)." (PMID 30914949, 2019). "Patients with BLMH rs1050565 G/G genotype experienced severe pain, and patients with GSTP1 G/G genotype were susceptible to severe infections." (PMID 30914949, 2019). "GSTT1-null genotype was associated with lymphocytopenia, BLMH rs1050565 G/G genotype was linked with pain in a recessive model of inheritance and GSTP1 rs1695 G/G genotype was associated with infections in a recessive model of inheritance." (PMID 30914949, 2019).
BLMH also shares sentences with these, for which no sentence is quoted: Dry skin (2 papers); fibrosis (1); lymphoma (1); neuroblastoma (1); psoriasis (1); pulmonary fibrosis (1); testicular cancer (1); vulvar cancer (1).